KRAS (KRas proto-oncogene, GTPase)
Diseases named in the same sentence as KRAS in open-access papers (continued):
Sharing a sentence is not in itself a finding about the gene and the disease.
lung cancer (continued). "Systematic genome analyses revealed that LKB1 loss suppresses dipeptidyl peptidase 4 (DPP4) expression and activity in KRAS-mutant lung cancer." (PMID 41283988, 2025). "This phenomenon is recapitulated in KRAS‐driven lung cancer models, where CD206+ M2‐polarized TAMs coexpress the senescence marker p16." (PMID 41427020, 2025). "Mutations in KRAS have been detected in up to 25% of cases of NSCLC, which accounts for 85% of all lung cancer cases." (PMID 39960727, 2025). "Further tentative support for the efficacy of NK cells against lung cancer (LC) was derived from a laboratory investigation involving Kirsten rat sarcoma viral oncogene homolog (KRAS)-driven spontaneous LC and the implantation of cancer cells into mice." (PMID 41350490, 2025). "KRAS proto-oncogene, GTPase (KRAS)-liver kinase B1 (LKB1)–mutant (KL) non–small cell lung cancer (NSCLC), characterized by a profoundly immunosuppressive tumor microenvironment (TME), is highly resistant to immune checkpoint inhibitors." (PMID 41283988, 2025). "In nonsmall cell lung cancer (NSCLC), various genetic aberrations have been studied for their association with VTE, including ALK fusions, KRAS mutations, and EGFR mutations." (PMID 39851266, 2025). "For example, in a KRAS-driven lung cancer model, treatment with phenformin significantly prolonged survival in mice-but only when the tumors lacked LKB1." (PMID 41050082, 2025). "The STRING protein–protein interaction (PPI) analysis of EGFR, ALK, KRAS, and PD-1 revealed a complex, yet functionally coordinated molecular landscape in lung cancer." (PMID 40927719, 2025). "Transcriptomics profiling reveals upregulation of GFPT2 in mesenchymal stem cells within KRAS-driven lung cancer models." (PMID 40830088, 2025). "In a lung cancer mouse model, secretion of IL-6 by KRAS-mutant tumor cells correlated with increased numbers of M2 TAMs and tumor growth." (PMID 40524071, 2025). "Another KRAS G12D inhibitors called MRTX1133 has been developed to target GTPase activity in KRAS G12D-driven lung cancer, pancreatic and colorectal adenocarcinoma models." (PMID 39820726, 2025). "Further studies based on mouse lung cancer models and human cancer cell lines demonstrated that TBK1 signaling-regulated CCL 5 and IL-6 promote KRAS-driven NSCLC by affecting lung cancer cell proliferation and the local inflammatory microenvironment." (PMID 40076567, 2025). "Studies on lung cancer have also shown that TBK1 signaling was essential for the survival of KRAS-driven lung cancer cells, which is dependent on TBK1-AKT/mTOR signaling-mediated tumor growth and immunosuppression." (PMID 40076567, 2025). "The findings demonstrate the utility of combining interpretable machine learning models with virtual screening to accelerate the discovery of potent KRAS inhibitors for lung cancer therapy." (PMID 41333851, 2025). "Developing combination therapy strategies for KRAS-mutant lung cancer is crucial to achieving more durable clinical outcomes." (PMID 40885709, 2025). "REGγ has been implicated as an oncogene that promotes malignant transformation in KRAS-mutant lung cancer." (PMID 40091835, 2025). "In lung cancer, particularly non-small cell lung cancer (NSCLC), oncogenic alterations such as mutations in KRAS, EGFR, BRAF, and ALK rearrangements activate key signaling cascades, most notably the RAS–RAF–MEK–ERK and PI3K-AKT–mTOR pathways." (PMID 40823246, 2025).
lung cancer (continued). "For instance, in KRAS-driven lung cancer, senescent macrophages accumulate in tumor tissues as tumors progress and depletion of senescent macrophages ameliorates tumorigenesis by enhancing immunosurveillance by effector T cells." (PMID 39834857, 2025). "Our study identifies a new epigenetic mechanism involving the ANP32A that promotes KRAS-mutant lung cancer growth and affects Sot activity." (PMID 41475546, 2025). "Glucose-6-phosphate dehydrogenase (G6PD), the rate-limiting enzyme, regulates NADPH/NADP + ratios and is implicated in tumorigenesis, particularly in KRAS-driven, LKB1-deficient lung cancer." (PMID 40734168, 2025). "Although lung cancer cell lines demonstrate a decrease in KRAS levels, activation of the MAPK pathway kinases MEK1/2, ERK 1/2, and p90RSK is observed after treatment with the PCAIs." (PMID 40736275, 2025). "Given the critical role of KRAS in lung cancer and other cancers, it remains as a major target for the development of new and complementary treatments." (PMID 40890128, 2025). "Radiomic features of another less-used imaging modality in lung cancer—that of MRI for brain metastases—have also been used to predict specific genetic mutations, such as EGFR, ALK, and KRAS, with AUC of over 0.9, as well as OS." (PMID 40075729, 2025). "Compared to the 39% of patients’ samples with driver mutations and alterations who underwent sequencing of lung carcinomas at our institution, 76% of patients with CNS metastases harbored driver mutations and alterations, predominantly EGFR, KRAS, and ALK." (PMID 40423053, 2025). "No specific NRAS inhibitor has been approved, but promising results have emerged with naporafenib, an inhibitor of KRAS and NRAS-mutated tumors (in lung carcinoma and melanoma)." (PMID 40423070, 2025). "KRAS mutant lung cancer, characterized by dysregulated KRAS signaling pathways, exhibits distinct metabolic alterations to meet the increased energy demands and biosynthetic requirements of proliferating cells." (PMID 38802900, 2024). "Genetic ancestry is associated with specific somatic driver mutations in EGFR, KRAS, and STK11 in lung cancer in individuals of Indigenous American ancestry relative to those of EUR or EAS ancestry." (PMID 38836758, 2024). "To further our understanding of the effects of PCAIs on the NCI-H23 lung cancer cells, we probed for proteins further downstream of KRAS by western blotting." (PMID 39436906, 2024). "First, we assessed the effects of HOXC10 knockdown on cancer cell growth in KRAS-mutant lung cancer bone metastasis cell lines." (PMID 39191757, 2024). "The DVC system was used to measure circadian activity changes indicative of lung cancer progression in KRAS and KRAS-LKB1 transgenic mouse models." (PMID 39763604, 2024). "Recently, allele-specific inhibitors were approved for the treatment of KRAS-G12C mutant lung cancer." (PMID 38278976, 2024). "Clinical trials on the mutant KRAS-targeted long peptide vaccine for high-risk pancreatic cancer recipients and EGFR-targeted vaccine for high-risk lung cancer recipients are currently underway (NCT05013216, NCT04298606)." (PMID 38890350, 2024). "Using a variety of in vivo systems, including allografts, orthotopic transplantation and KRAS-driven lung cancer mouse models, we demonstrate that transient reprogramming by OSKM expression in cancer cells impairs tumor growth and reduces tumor burden." (PMID 39587064, 2024). "Here we use an inhibitor, (RMC-4998) that targets RASG12C in its active, GTP-bound form, to treat KRAS mutant lung cancer in various immune competent mouse models." (PMID 39322643, 2024).
lung cancer (continued). "We further validate our findings in vivo using allograft and orthotopic transplantation of lung tumor cells as well as a genetically modified mouse model of KRAS-driven lung cancer." (PMID 39587064, 2024). "We have previously identified MGA as a driver event that cooperates with mutant KRAS to promote lung cancer in vivo." (PMID 39052387, 2024). "Knock-out of SIK1 and SIK3 increased tumor growth in a mouse model of oncogenic KRAS-driven lung cancer." (PMID 39544365, 2024). "COX2 signaling via prostaglandin E2 is a major mediator of immune evasion driven by oncogenic KRAS that promotes immunotherapy and KRAS-targeted therapy resistance, suggesting effective combination treatments for KRAS-mutant lung cancer." (PMID 38635884, 2024). "We employed the lightweight CNN model to classify patient-derived lung cancer cells, both categorized as adenocarcinomas but with distinct genetic profiles: one harboring the KRAS oncogene (HCC 4087) and the other the EGFR oncogene (HCC 4190)." (PMID 39180048, 2024). "Conversely, KRAS is a well-established oncogene, intimately involved in carcinogenesis in most cancers, including lung cancer." (PMID 39734333, 2024). "RNA-seq was conducted in KRAS-mutant lung cancer bone metastasis cells of H441-BM upon HOXC10 knockdown." (PMID 39191757, 2024). "These candidates have shown clinical success in inhibiting KRAS in lung cancer as well as in preclinical-stage pancreatic cancer." (PMID 39062777, 2024). "There is growing evidence that PD-L1 expression in lung cancer is upregulated intrinsically through activation of the downstream KRAS signaling pathways." (PMID 39690423, 2024). "Although HOXC10 inhibition showed promising benefits in KRAS-mutant lung cancer bone metastasis in vivo, we found that the ability of inhibiting bone metastasis by HOXC10 knockdown was significantly diminished 28 days after intracardiac injection." (PMID 39191757, 2024). "When it comes to KRAS-mutant lung cancer, researchers elucidated the importance of accurate and timely determination of KRAS status in guiding treatment decisions for NSCLC." (PMID 38706597, 2024). "Collectively, these findings demonstrate that HOXC10 depletion can suppress proliferation and migration and promote apoptotic ability in KRAS-mutant lung cancer bone metastasis cells." (PMID 39191757, 2024). "We measured the apoptotic capacity by Annexin V staining and observed that the apoptosis of KRAS-mutant lung cancer bone metastasis cells increased 5.2-fold to 15.6-fold after HOXC10 knockdown." (PMID 39191757, 2024). "Recently, lipid nanoparticles carrying KRAS siRNAs reduced its expression in several lung cancer cell lines, including human (A549 and H441) and mouse (CMT-167 and Lacun3) cells, and proliferation was observed through colony-forming assays." (PMID 38893088, 2024). "Direct targeting of the KRAS-G12C–mutant protein using covalent inhibitors (G12Ci) acts on human non–small cell lung cancer (NSCLC)." (PMID 39661665, 2024). "KRAS-mutant lung cancer bone metastasis tumors showed higher sensitivity to cotreatment with MEK162 and TTI-101 than monotherapy." (PMID 39191757, 2024). "EGFR, ALK, VEGF, and KRAS are the most important signaling pathways which have been identified and are involved in the progression of lung cancer." (PMID 38234663, 2024).
lung cancer (continued). "This also underscores the need for personalized therapies tailored to different subgroups of KRAS-driven lung cancers, especially when considering the application of G6PD inhibitors in cancer treatment." (PMID 38997257, 2024). "Strikingly, inhibition of HOXC10 in combination with STAT3 inhibitor was effective against KRAS-mutant lung cancer bone metastasis by triggering ferroptosis." (PMID 39191757, 2024). "Ferredoxin 1, as a central mediator in cellular redox regulation and metabolism, likely plays a pivotal role in orchestrating these metabolic adaptations in KRAS mutant lung cancer." (PMID 38802900, 2024). "The G12C mutation, which is present in 16% of all lung adenocarcinomas, is the most frequent change in KRAS in lung cancer." (PMID 38234663, 2024). "KRAS is prevalent in various regions of lung cancer tissues in Caucasian populations, even after subregional molecular testing of patient tumor tissues after sectioning." (PMID 38313018, 2024). "Enhancing or losing ALKBH5 function effectively reverses the regulation of proliferation, colony formation, and migration of KRAS-mutant lung cancer cells by LKB1." (PMID 39192357, 2024). "The combination of SHP2 and MEK inhibitors has a highly synergistic anti-proliferative impact in KRAS mutant lung cancer and pancreatic cancer." (PMID 38504984, 2024). "In the tested lung cancer samples from Mexican patients, the mutation frequencies of EGFR and KRAS were 30 and 10%, respectively, while in Colombian patients, these frequencies were 23 and 13%." (PMID 38581481, 2024). "Here, we found that in KRAS-driven lung cancer, FAK activation is synergistically controlled by ERK5 and CDK5." (PMID 39271958, 2024). "Significance: COX2 signaling via prostaglandin E2 is a major mediator of immune evasion driven by oncogenic KRAS that promotes immunotherapy and KRAS-targeted therapy resistance, suggesting effective combination treatments for KRAS-mutant lung cancer." (PMID 38635884, 2024). "To explore the key genetic alterations in bone metastasis of KRAS-mutant lung cancer development, we applied RNA sequencing (RNA-seq) to compare metastatic lung cancer cell line H441-BM with primary lung cancer cell line H441." (PMID 39191757, 2024). "CDK-2 inhibition has been considered in the treatment of highly aneuploid cancers, especially in KRAS-mutant lung cancer." (PMID 38184514, 2024). "The roles of lung cancer-related genes, such as KRAS, EGFR, and ALK, have been systematically investigated in specific animal models of cancers." (PMID 39311119, 2024). "Another miRNA dysregulated in PC and targeting KRAS is hsa-miR-877-5p, which has previously been reported as a marker of bone metastasis in lung cancer and is overexpressed in hepatocellular carcinoma." (PMID 39057123, 2024). "In this study, CRISPR/Cas9-mediated knockdown of PD-L1 and KRAS was investigated as a therapeutic approach for the treatment of lung cancer." (PMID 39201772, 2024). "Altogether, this study reveals a previously unrecognized role of HOXC10 in pan-KRAS-mutant lung cancer bone metastasis, and suggests HOXC10 as a therapeutic target for treating this intractable disease." (PMID 39191757, 2024). "It is thus imperative that we identify therapies to treat KRAS-driven lung cancers that are effective in Black lung adenocarcinoma patients." (PMID 39436906, 2024).
lung cancer (continued). "Studies show that circadian disruption (chronic jetlag) can lead to increased tumor burden in KRAS (Ki-ras2 Kirsten rat sarcoma viral oncogene homolog)-driven lung cancer mouse models, potentially through the upregulation of heat shock factor 1 target genes." (PMID 39062777, 2024). "LKB1 inactivation in KRAS mutant lung cancer cells promotes glutaminolysis and facilitates the formation of glutamine-derived succinate, fumarate and malate in the later stages of TCA cycle, thus promoting mitochondrial oxidative phosphorylation." (PMID 39544365, 2024). "In lung cancer patients with KRAS WT, except for MTHFD1, the expression levels of G6PD, IDH1, and ME1 were not correlated with the patient survival time." (PMID 38997257, 2024). "In this study, transgenic animal models of lung cancer harboring KRAS/LKB1 and KRAS mutations were used." (PMID 39763604, 2024). "KRAS/LKB1–mutant lung cancer cells suppress STING expression, wherein exogenous expression of STING led to the detection of cytoplasmic mitochondrial DNA, induction of TBK1/IRF3 innate signaling, and decreased cell fitness." (PMID 38226619, 2024). "Among the KRAS-wild type lung cancer cell lines analyzed, trametinib only impaired the viability of the H1437, a cell line that harbors MAP2K1 mutation." (PMID 38643157, 2024). "STING signaling is suppressed in several cancers, including melanoma, colon cancer, and KRAS/LKB1–mutant lung cancer, perhaps as a consequence of STING’s role in antitumor immunity and sensing of DNA damage." (PMID 38226619, 2024). "This is the first in vivo transcriptional evidence that, similarly to KRAS-mutant AT2 cells, AT2 cells carrying EGFR mutations act as lung cancer cells of origin." (PMID 38546390, 2024). "The crucial role of STAT3 pathway in MEKi resistance is also supported by a recent study demonstrating the synergistic effect of STAT3i and MEKi in KRAS-mutant lung cancer." (PMID 39191757, 2024). "Altogether, these results demonstrate that HOXC10 inhibition and TTI-101 combination has dramatic effects on key ferroptosis mediators in KRAS-mutant lung cancer bone metastasis cells, including cellular ROS and GSH levels." (PMID 39191757, 2024). "KRAS mutant lung cancers appear to acquire radiation therapy resistance through EGFR-mediated chromatin condensation, thereby blocking induction of DSBs." (PMID 39095874, 2024). "Intriguingly, inhibition of HOXC10 plus STAT3 inhibitor in combination was effective against KRAS-mutant lung cancer bone metastasis by triggering ferroptosis." (PMID 39191757, 2024). "Here, we identified homeobox C10 (HOXC10) as a lynchpin in pan-KRAS-mutant lung cancer bone metastasis." (PMID 39191757, 2024). "BACH1 activates the transcription of glycolytic enzymes hexokinase 2 (HK2) and GAPDH, thus increasing glucose uptake, glycolysis rates, and lactate secretion to promote KRAS-driven lung cancer metastasis." (PMID 39061897, 2024). "Our data demonstrate the therapeutic benefits of genetic ablation or pharmacologic inhibition of COX2 in a preclinical model of KRAS-mutant lung cancer, especially in combination with immunotherapy." (PMID 38635884, 2024). "We recently developed a novel immunogenic model of KRAS-mutant lung cancer, allowing for the preclinical study of tumor–immune interactions." (PMID 38635884, 2024). "LKB1 inactivation in KRAS mutant lung cancer cells enhances glycolysis and serine biosynthesis and protects cell survival from serine deprivation through deregulated AMPK-mTORC1 signaling." (PMID 39544365, 2024). "In the specific context of KRAS mutant lung cancer, aberrant KRAS signaling drives metabolic rewiring, promoting aerobic glycolysis (the Warburg effect), glutamine addiction, and altered lipid metabolism to fuel tumor progression." (PMID 38802900, 2024). "Its heightened signaling contributes to the development of resistance to KRAS inhibition in lung cancer." (PMID 39431199, 2024).